TREX1 (three prime repair exonuclease 1)
Diseases named in the same sentence as TREX1 in open-access papers (continued):
Sharing a sentence is not in itself a finding about the gene and the disease.
autoimmune disease (continued). "Existing structures of mouse TREX1 establish a mechanism of DNA degradation and provide a key model to explain autoimmune disease, but these structures incompletely explain human disease-associated mutations and have limited ability to guide development of small-molecule therapeutics." (PMID 35879334, 2022). "Injection of miR-23a/b agomirs ameliorated the disease phenotype of Trex1−/− mice, providing evidence that miR-23a/b might be a new therapeutic target for autoimmune diseases." (PMID 33767433, 2021). "So far, the most promising cGAS inhibitor came from synthesized AMD derivative X6, which could attenuate the autoimmune disease phenotype in Trex1−/− mice." (PMID 33968056, 2021). "Furthermore, PAH administration alleviates autoinflammatory responses in Trex1−/− bone marrow-derived macrophages (BMDMs) and the autoimmune disorder in Trex1−/− mice." (PMID 33968056, 2021). "Also, the TOLLIP deletion decreases the STING-dependent autoimmune disease in three prime repair exonuclease 1 knockout (KO) or Trex1-/- mice." (PMID 33643304, 2020). "TREX1 prevents the L1 retrotransposon-induced DNA damage response, and mutations in RNases and a DNase, TREX1 has been linked with SLE, also known as Aicardi-Goutières syndrome, and other autoimmune diseases such as Sjögren’s syndrome and systemic sclerosis." (PMID 29867148, 2018). "TREX1 is an excellent example of a protein that may bridge this gap in our knowledge by playing important roles in both infectious and autoimmune diseases." (PMID 24817865, 2014). "The other 5 variations are synonymous and only one of them is novel (p.Pro48Pro).This study contributes to the demonstration that TREX1 is involved in autoimmune diseases and proposes that the spectrum of involved autoimmune diseases can be broader and includes SSc." (PMID 24224166, 2013). "This work stems from recent papers which strongly suggest a role of TREX1 in autoimmune diseases." (PMID 24224166, 2013). "Notably, many variants with reported pathogenic effects in patients with autoimmune disease (e.g., D18N, R114H, V201D) and many other protein-altering variants which interfere with TREX1 function were not reported in any TCGA or COSMIC cancer samples." (PMID 40581636, 2025). "While many TREX1 variants with suggested pathogenic effects in germline autoimmune disease were not reported in tumor samples or cancer cell lines, some amino acid substitutions in cancer samples occur at positions that are highly conserved across placental mammals." (PMID 40581636, 2025). "Currently, no specific treatment is available for autoimmune diseases with TREX1 mutations." (PMID 39254994, 2024). "Additionally, >60 patient mutations in TREX1 have been identified as associated with the autoimmune disease with many mutations occurring in hTREX1 positions not shared with mTREX117,31." (PMID 35879334, 2022). "In addition, we investigated whether activated ER stress signaling in TREX1-deficient cells occurs through the STING pathway, a known pathway associated with TREX1-deficient autoimmune diseases." (PMID 34997539, 2022). "As Trex1−/− mice are mechanistically characterized by aberrant activation of cGAS, we sought to determine whether miR-23a/b could be utilized to treat cGAS-mediated autoimmune diseases." (PMID 33767433, 2021). "Thus, preventing cGAS-STING activation could provide therapeutic benefit to treat TREX1-mediated autoimmune disease." (PMID 33868310, 2021). "In addition, miR-23a/b treatment was effective in alleviating cGAS-mediated autoinflammatory responses in the Trex1−/− mouse model, indicating that miR-23a/b could be used to treat self DNA-induced autoimmune diseases." (PMID 33767433, 2021). "Moreover, cGAS is significantly upregulated in the Trex1−/− mouse autoimmune disease model." (PMID 33767433, 2021).
autoimmune disease (continued). "Although we demonstrated that PA significantly mitigates interferon and ISG production in ADAR1- and Trex1-related AGS models, substantial efforts should be undertaken to examine the effect of PA on AGS and other autoimmune diseases in vivo." (PMID 40149865, 2025). "The in vivo data demonstrated that Ginkgetin effectively alleviated systemic inflammation in Trex1−/− mice, indicating its potential to improve STING‐dependent autoimmune diseases." (PMID 39558862, 2024). "In particular, this work aims to replicate in the Italian population the involvement of TREX1 in SLE and SS, and to extend the investigation to a further autoimmune disease." (PMID 24224166, 2013). "However, in autoimmune diseases such as AGS and SLE, TREX1 dysfunction leads to cytosolic DNA accumulation, resulting in persistent activation of the cGAS–STING pathway and excessive inflammatory responses in multi-organ." (PMID 40595456, 2025). "TREX1 prevents excessive accumulation of endogenous auto-DNA and prevents aberrant activation of DNA-mediated cGAS-STING signaling, while structurally inactivated TREX1 leads to the IFN-dependent autoimmune disease AGS." (PMID 36172373, 2022). "ALR activation is not essential for inducing type 1 IFN production in response to the cytosolic DNA and also does not contribute to the autoimmune disease in the Trex1-/- mice with AGS." (PMID 33643304, 2020). "Importantly, we show that targeting cGAS demethylation, either through K350R mutation or KDM4B inhibition with JIB-04, ameliorates autoimmune manifestations in both Trex1−/− mice and AGS patient PBMCs, presenting a promising therapeutic strategy for self-DNA-induced autoimmune disorders." (PMID 40595456, 2025). "However, when TREX1-mediated LINE-1 suppression was first linked to the development of autoimmune diseases, azidothymidine (AZT, an NRTI that is widely used in HIV treatment) was tested and found to not ameliorate the inflammatory symptoms detected in TREX1 knockout mice." (PMID 34566998, 2021).
Autoimmunity (45 papers, 2009 to 2026). The occurrence of an immune reaction against the organism's own cells or tissues. "In vivo, hematopoietic cells were suggested as a source of type I IFNs; TREX1 deficiency in hematopoietic cells was necessary and sufficient to drive autoimmunity in adoptive transfer experiments." (PMID 39254994, 2024). "In contrast, our study shows that cGAS in macrophages was dispensable for autoimmunity caused by TREX1 deficiency." (PMID 39254994, 2024). "Similar to human patients with Trex1 mutations, Trex1–/– mice develop lethal autoimmunity characterized by type I IFN-dependent inflammation." (PMID 39254994, 2024). "A previous study reported that the deletion of the Trex1 gene in Clec9a-expressing cells is sufficient to cause autoimmunity." (PMID 39254994, 2024). "Trex1 is the major 3′-exonuclease in human cells and is mutated in certain patients with autoimmune disorders." (PMID 35357486, 2022). "Considering that cGas-Sting axis mediates autoimmune phenotypes in Trex1−/− mice, we investigated the roles of Irf8 in autoimmunity in Trex1-deficient mice." (PMID 35973990, 2022). "Together our results reveal the structure of human TREX1 and establish a model to explain how human-specific substitutions regulate TREX1 activity and are impacted in TREX1-associated autoimmunity." (PMID 35879334, 2022). "Expectedly, knockout of ARIH1 in myeloid cells fully rescued the autoimmune lethality caused by TREX1 deficiency, suggesting that ARIH1 in myeloid cells sufficiently supports autoimmunity caused by dysfunction of TREX1." (PMID 36217001, 2022). "Mice known to develop spontaneous autoimmunity, such as Faslpr, Sanroque and Trex1-deficient mice, had varying frequencies of splenic plasmablasts (representative dot plots and bar graphs)." (PMID 35651611, 2022). "Trex1, discovered in 1969 and purified three decades later, has been studied extensively for its role in preventing autoimmunity caused by excess of ssDNA in the cytosol." (PMID 35701408, 2022). "Overall cytosolic TREX1, RNase H2 and NA-editing enzymes regulate the potential of endogenous DNA and RNA to causes inflammatory and autoimmune disorders." (PMID 33717156, 2021). "TREX1-deficient mice display markedly reduced survival due to unprompted inflammatory myocarditis, increased circulatory failure and cardiomyopathy Trex1 prevents the cell-intrinsic initiation of autoimmunity in the mice model of TREX1-deficient mice." (PMID 31440232, 2019). "Taken together, these findings suggest mutations in and dysregulation of TREX1 have the potential to lead to inappropriate activation of the immune system and development of autoimmunity." (PMID 26257198, 2015). "Clearly, the biological significance of monoubiquitination on native or disease-causing forms of TREX1 for viral DNA sensing and autoimmunity requires further investigation." (PMID 24817865, 2014). "TREX1 regulates the cGAS immune sensing pathway by reducing the cytosolic DNA level; thus, the loss-of-function of TREX1 causes overactivation of cGAS by endogenous DNA and leads to autoimmunity." (PMID 39254994, 2024). "Short interspersed nuclear elements, long interspersed nuclear elements, and long terminal repeats, which are derived from endogenous retroelements, accumulate in Trex1-deficient mice suggesting that TREX1 functions to prevent the development of autoimmunity through degrading such DNA species." (PMID 34258050, 2021). "In TREX1-deficient cells, self-DNA accumulates in the cytosol and leads to inappropriate activation of chronic type I interferons, which can break immune tolerance and promote autoimmunity or autoinflammatory diseases." (PMID 32293470, 2020). "Moreover, while loss of only one allele of cGAS was sufficient to ameliorate autoimmunity/cardiomyopathy in Trex1 knockout mice, knockout of both cGAS alleles was needed to prevent polyarthritis in DNase III knockout mice." (PMID 28679751, 2017).
Autoimmunity (continued). "Thus, ultraviolet light could create a vicious cycle that fuels and sustains autoimmunity in TREX1 deficiency." (PMID 27230542, 2016). "TREX1, located on the cytoplasmic face of the ER, functions as a 3′ to 5′ exonuclease, degrading cytosolic DNA to prevent persistent cGAS activation and autoimmunity." (PMID 41153813, 2025). "Cyclic GMP-AMP (cGAMP) synthase (cGAS) has been shown to mediate this autoimmunity by detecting cytosolic DNA, and inhibitors targeting the cGAS pathway reduce inflammation and disease phenotypes in Trex1–/– mice." (PMID 39254994, 2024). "TREX1 is an exonuclease that degrades cellular and viral cytoplasmic DNAs to prevent autoimmunity and viral infections." (PMID 36851531, 2023). "The downregulation of TREX1 in CD11c+ myeloid DCs was sufficient to induce autoimmunity in mice highlighting the importance of myeloid DCs for the induction of autoimmunity." (PMID 35911727, 2022). "To assess the possibility of miR-23a/b for the treatment of cGAS-mediated autoimmunity, we first transfected miR-23a/b mimics or control mimics into BMDMs isolated from WT and Trex1−/− mice." (PMID 33767433, 2021). "Fatal autoimmunity in Trex1 KO was rescued by the deletion of the cGAS-STING pathway, indicating that absence of TREX1 results in aberrant activation of DNA sensing pathways." (PMID 33717156, 2021). "Previous reports addressing the link of the STING pathway with autoimmunity have provided varied views: STING is essential for the phenotype of Trex1−/− mice in which accumulation of endogenous DNA substrates triggers production of type I IFNs." (PMID 31681326, 2019). "Several genes, such as TREX1, FLI1, EVI5, IL1RAPL1, are known for their role in autoimmunity, with EVI5 being an established MS risk gene, whereas others, such as CBFB, OPCML and KMT2A, are involved in lymphoproliferative disorders (OMIM)." (PMID 30541027, 2019). "Recent studies have suggested that TREX1 suppresses the activation of the endogenous DNA sensor cGAS and prevents autoimmunity by reducing cytosolic DNA, especially retroelement DNA." (PMID 28334850, 2017). "In fact, coincident with reducing the levels of L1 ORF1p protein, TREX1 also suppressed L1-induced genome nicking, as shown by the comet assay, suggesting a novel way for TREX1 to prevent autoimmunity." (PMID 28334850, 2017). "In TREX1 deficiency, type I IFN activation and autoimmunity result from immune recognition of unmetabolized cytosolic ssDNA." (PMID 27230542, 2016). "Furthermore, given that TREX1 functions to degrade DNA, the missense mutation may be responsible for defective DNA degradation during apoptosis, leading to abnormal clearance of DNA and induction of autoimmunity." (PMID 26257198, 2015). "TREX1-deficient mice, known to develop type I IFN-dependent autoimmunity, display upregulation of type I IFN-dependent genes in the skin and cutaneous deposition of immunoglobulins and complement." (PMID 26257198, 2015). "TREX1 is a DNase responsible for degrading cytosolic DNA and plays a crucial role in preventing self-DNA-induced autoimmunity." (PMID 38578631, 2024). "In summary, our study identified cDCs as the major driver of autoimmunity in Trex1-/– mice." (PMID 39254994, 2024). "Since TREX1 degrades DNA in the cytosol whereas DNase II degrades DNA in the lysosome, the type of cells driving autoimmunity via cGAS activation may depend on the subcellular localization of self-DNA." (PMID 39254994, 2024). "Furthermore, selective loss of the Trex1 gene in Clec9a-expressing cells was sufficient to induce autoimmunity, indicating that deletion of Trex1 in cDC1 is sufficient to drive autoimmunity." (PMID 39254994, 2024). "The first mutations were found in the three prime repair DNA exonuclease 1 (TREX1) and cause monogenic familial chilblain lupus (FCL), Aicardi Goutières syndrome, a type I interferonopathy with features of autoimmunity, and represent a risk factor for the development of SLE." (PMID 35911727, 2022).
Autoimmunity (continued). "Lastly, we detected the increment of phosphorylated proteins related to T lymphocyte response (e.g., Rho family-interacting cell polarization regulator 2) and the prevention of the cell-intrinsic initiation of autoimmunity (e.g., three-prime repair exonuclease 1)." (PMID 34712240, 2021). "Mice null for Trex1 develop a lethal autoimmunity and die by 9 weeks." (PMID 34258050, 2021). "TREX1 dysfunction activates the cGAS-STING DNA-sensing pathway resulting in autoimmunity." (PMID 33868310, 2021). "In summary, we have discovered and characterized a small molecule that shows potent and selective inhibition of cGAS dsDNA-dependent enzymatic activity in vitro and in cells, including primary macrophages taken from a Trex1 null mouse model of AGS autoimmunity." (PMID 28963528, 2017). "However, although being associated with activation of autoimmunity and autosomal-dominant AGS, the TREX1 mutant D200N has been reported as exonuclease active yet with no potency to suppress L1 retrotransposition." (PMID 28334850, 2017). "Mutations in the exonuclease TREX1 cause type I IFN-dependent autoinflammation and autoimmunity." (PMID 27230542, 2016). "Also, both proteins attenuate autoimmunity, and patients carrying defective TREX1 or SAMHD1 develop similar autoimmune and sterile inflammatory phenotypes." (PMID 24817865, 2014). "TREX1 deficient cells accumulate cytoplasmic DNA derived from endogenous retroelements, which can then activate IRF3 to trigger production of type I IFNs leading to autoimmunity." (PMID 19266025, 2009). "Indeed, DNA damage lies at the heart of a separate TREX1-mediated disease, known as retinal vasculopathy with cerebral leukoencephalopathy, where the aberrant nuclear activity of mislocalized TREX1 damages genomic DNA, resulting in multi-organ degeneration syndrome with features of autoimmunity." (PMID 42222883, 2026). "This is consistent with TREX1’s role as an immune inhibitor that prevents cGAS-STRING initiation, with inhibition of TREX1 stimulating IFN signaling and autoimmunity, making it a potential immunomodulatory target." (PMID 37173324, 2023). "Three-prime repair exonuclease 1 (TREX1) is a 3′-to-5′ exonuclease that degrades DNA to prevent aberrant nucleic acid sensing and the resulting autoimmunity." (PMID 37339225, 2023). "One of these strategies involves the three prime repair exonuclease 1 (TREX1), the most abundant DNA 3′→5′ exonuclease in human cells, involved in the degradation of small DNA fragments to antagonize the cGAS-STING pathway and prevent severe autoimmunity." (PMID 39177280, 2024). "Furthermore, while TREX1 has been shown to participate in systemic autoimmune diseases (i.e., AGS and SLE), its role in organ-specific autoimmunity (i.e., multiple sclerosis, psoriasis, type 1 diabetes, etc.)has yet to be determined." (PMID 34072535, 2021). "In another study analyzing autoimmunity in the absence of functional TREX1, Thomas and colleagues generated pluripotent stem cells from AGS patients to analyze the consequences of TREX1 deficiency in human neuronal cells." (PMID 33445593, 2021). "In contrast to Trex1−/− and Adar1−/− mice, SAMHD1-deficient mice did not develop detectable pathology or autoimmunity." (PMID 23972988, 2013). "However, treating TREX1 KO mice with the HIV reverse transcriptase (RT) inhibitor AZT did not ameliorate autoimmunity." (PMID 33445593, 2021). "In the absence of TREX1 exonuclease activity, substrate accumulation stimulates the DNA-sensing pathway cGAS-STING, which drives IFN-signaling and autoimmunity." (PMID 33868310, 2021).
familial chilblain lupus (30 papers, 2011 to 2025). An instance of Chilblain lupus that is caused by an inherited modification of the individual's genome. "Genetic variants of Three Prime Repair Exonuclease 1 (TREX1), another gene involved in DNA repair and degradation, have been previously linked to familial chilblain lupus and SLE." (PMID 39335717, 2024). "Ruxolitinib has also been shown to be effective in the treatment of lesions in patients with familial chilblain lupus with TREX1 mutations." (PMID 37828538, 2023). "It involves TREX1 mutations in an autosomal dominant form and it is related to early-onset familial chilblain lupus." (PMID 36468094, 2022). "In some cases such as familial chilblain lupus the underlying cause can be TREX1 gene mutations leading to a dysfunctional TREX1 exonuclease and high accumulation of cytosolic DNA." (PMID 32194562, 2020). "Mutations in TREX1 are associated with familial chilblain lupus and are also associated with the inflammatory disorder Aicardi-Goutieres syndrome." (PMID 29975701, 2018). "One additional TREX1-associated type I interferonopathy is familial chilblain lupus (FCL)." (PMID 41425849, 2025). "Also, TREX1-associated familial Chilblain-Lupus is caused by a loss of function mutation in TREX1 which leads to activation of the type I IFN system." (PMID 34381458, 2021). "Mutations in TREX1 have also been associated with other diseases, such as retinol vasculopathy with cerebral leukodystrophy (RVCL) and Familial Chilblain Lupus." (PMID 34519260, 2021).